MTOR (mechanistic target of rapamycin kinase)
Diseases named in the same sentence as MTOR in open-access papers (continued):
Sharing a sentence is not in itself a finding about the gene and the disease.
tumor (continued). "Combination treatment with the mTOR inhibitor rapamycin significantly recovered the tumor numbers." (PMID 32290362, 2020). "Activated aberrant PI3K/AKT/mTOR signaling pathway results in tumor growth and survival." (PMID 32578154, 2020). "One study showed that upregulated PD-L1 on tumor cells promotes mammalian target of rapamycin (mTOR) activity and glycolytic metabolism, which leads to tumor-mediated glucose restriction, alters CD8+ T-cell metabolism, and dampens the ability of T cells to produce IFN-γ." (PMID 32775303, 2020). "Interestingly, tumor cells with chronic PI3K/mTOR inhibition are able to resume proliferation through CREB stabilization." (PMID 33046706, 2020). "The relationship between p16 and activating mutation markers could influence the stepwise progression of tumor cells, inhibiting the mammalian target of rapamicin (mTOR) pathway and downstream activation of hypoxia factor." (PMID 32945604, 2020). "Finally, although M2BPGi treatment enhanced the proliferation of HCC cells, the tumour-promoting effects of M2BPGi were cancelled by treatment with the representative mTOR inhibitor rapamycin." (PMID 32624579, 2020). "Furthermore, fumarate and 2-HG evoke opposite effects on mTOR signaling, with consequences for the development of certain tumor types and potential indirect influence on radiation sensitivity." (PMID 32799884, 2020). "Additionally, hypoxia also induced the up-regulation of mTOR activity in T47D cells, indicating that hypoxia would continuously affect the inflammatory signaling in tumor cells." (PMID 33245358, 2020). "In terms of our findings, we may need to take into consideration the expression levels of AEBP1 in patients’ tumor samples when planning clinical trials of MTOR inhibitors on GBM or evaluating clinical responses of MTOR inhibitors in the treatment of GBM." (PMID 32938364, 2020). "This MDSC accumulation preferentially occur in tumor models exhibiting elevated mTOR activities." (PMID 33343560, 2020). "There is a clear dose-dependent inhibition of expression of both phosphorylated forms of Akt and phosphorylated 4EBP1 when they are normalized to total Akt or 4EBP1 protein, indicating inhibition of PI3K/mTOR important pathway in U87 MG GBM tumor tissue from mice administered PBI-05204." (PMID 33013390, 2020). "Nevertheless, the restored expression of EZH2 could reactivate AKT/mTOR pathway in the tumours formed by E2F7-silencing cells." (PMID 32814835, 2020). "However, the number of tumour types in which Hh and mTOR interact is as large as the variability of their postulated mutually interactions." (PMID 32751882, 2020). "Moreover, involvement of mTOR cascade in chemokine-mediated immune cells chemotaxis has recently been shown in different tumor types 59-61." (PMID 32483450, 2020). "The mTOR pathway plays a key role in several neoplasms, including PanNETs." (PMID 32850899, 2020). "Our data suggest that the tumour expression of galectin-3 may be a predictive factor of treatment outcomes, and could be used to select patients who would benefit from mTOR inhibitor therapy." (PMID 32624579, 2020). "Notably, we observed mTOR-dependent metabolic vulnerability in tumor cells from different NSCLC subtypes, Kras- and EGFR-driven LUAD." (PMID 32943635, 2020). "Thus, combined inhibition of YAP/TAZ and PDGFR signaling activity, BRD proteins and MEK activity, or the mTOR and Wnt/β-catenin pathways is strongly synergistic in blocking tumor growth, and can even induce apoptosis." (PMID 32315290, 2020). "The results indicated that tumor cells could quickly react to genotoxic stress by an mTOR-dependent pathway that reprogram the bioenergetics of the cells switching from aerobic glycolysis to mitochondrial oxidative phosphorylation." (PMID 32764667, 2020). "Furthermore, other compounds like escin, zerumbone, oxymatrine and formononetin also demonstrated anti-tumor effects via the inhibition of the AKT/mTOR pathway in several preclinical models." (PMID 32384682, 2020).
tumor (continued). "PTEN induces tumor suppression by negatively regulating the PI3K/AKT/mTOR signaling pathways." (PMID 32823871, 2020). "For example, the mTOR signaling pathway can affect gene transcription and protein synthesis to regulate cell growth and proliferation, affect the immune cell differentiation to participate in immune regulation, and play an important role in tumor metabolism." (PMID 32175074, 2020). "Globally, HIFs and mTOR pathway exert a tumor-promoting effect by intra-tumor immunosuppression." (PMID 32878021, 2020). "miR-100 is another miRNA which suppresses tumor growth by directly targeting mTOR." (PMID 33292283, 2020). "Therefore, we concluded that inhibition of JADE-1 on the AKT/mTOR pathway affects the stemness of PCSCs and suppresses tumor growth." (PMID 32351328, 2020). "Interestingly, high levels of mTOR expression can lead to apoptotic resistance by modulating several molecules, including Bcl-2 family members, and thus promoting tumor cell survival)." (PMID 33071785, 2020). "The possible elimination of the sub-clone harboring mutations in mTOR, PIK3CA and a FAT4 due to adjuvant chemotherapy could have happened either in the primary tumor or in the metastasis." (PMID 31953485, 2020). "Hence, co-targeting the BRD4 overexpressing cells with BET and PI3K /AKT/MEK/ ERK/ /mTOR inhibitors have been shown to affect cell proliferation, survival, and tumor growth significantly through activation of apoptosis compared to JQ1 alone." (PMID 33488950, 2020). "The rate of tumor progression in each of these acquired resistance models could only be impacted by the inclusion of a PI3K/mTOR pathway inhibitor in the treatment schedule." (PMID 32795346, 2020). "Furthermore, CRP targets to the p38/MAPK pathway causing lytic bone lesions and activates the PI3K/AKT/mTOR and the ERK/NF-κB pathway thereby inhibiting tumor cell apoptosis via the Fcγ receptor II in multiple myeloma." (PMID 33013829, 2020). "Additionally, via the p-AKT/p-mTOR pathway, fibrinogen promotes tumor progression via epithelial-mesenchymal transition." (PMID 33014783, 2020). "In addition, in a mouse CRC model, the combination of AZA and RPM reduced the incidence of CRC and the tumor volume, and decreased the activity of the mTOR signaling pathway." (PMID 32751889, 2020). "Moreover, delivery of miR-99b antagomir and siRNA against mTOR or κB-Ras2 into TAMs reduced tumor growth compared with miR-99b antagomir delivery." (PMID 32948650, 2020). "Phosphorylated Akt can induce mTOR to promote the motility and invasion of tumor cells." (PMID 32664703, 2020). "In addition, tumor signaling pathways that are regulated by BRAF, HIF-1α, c-MYC, and mTOR are accelerated to activate glycolysis in the cancer cells and accumulation of lactate in the microenvironment of the tumor." (PMID 32213878, 2020). "A wide variety of regulators have been identified in mechanistic target of rapamycin (mTOR) activation; however, the protective mechanisms of mTOR inactivation are still largely unknown, especially in tumor growth." (PMID 33377662, 2020). "Preclinical studies have also demonstrated that mTOR inhibitors—rapalogs may be related to the induction of signaling feedback loops limiting their anti-tumor effects." (PMID 31586300, 2020). "Interestingly, mTOR, Notch and Sonic Hedgehog promote self-renewal and survival of tumor-initiating cells by targeting PTEN." (PMID 32899927, 2020). "It was demonstrated that the mTOR inhibitor Everolimus, a rapamycin analog, could significantly inhibit tumor growth of DYRK2-depleted cells, compared to the control cells." (PMID 33081032, 2020). "However, in tumor cells, abnormally activated mTOR sends signals that encourage tumor cells to grow, metastasize, and invade new healthy tissues." (PMID 32175074, 2020). "Previous studies have shown that autophagy promotes tumor progression by inhibiting mTOR signaling." (PMID 31988807, 2020).
tumor (continued). "However, in our study, the PI3K/AKT/mTOR pathway was considered as a negative regulator for tumor progression and radiation resistance." (PMID 32373608, 2020). "The downstream effectors of abnormal activated PI3K/AKT pathway may contribute to its role in progression of tumor growth, apoptosis, altered endothelial cell function, and angiogenesis, such as NF-κB and mTOR." (PMID 32891122, 2020). "The mTOR inhibition could clearly slow down tumor growth and significantly extend the survival of animals by 35 days in average compared with sham treated controls." (PMID 32373532, 2020). "Whether such a mechanism could provide tumor cells with resistance to SB-699551, which inhibits both mTOR and AKT signaling pathways, remains unknown." (PMID 32758183, 2020). "Preclinical studies have demonstrated that abrogation of mTOR signalling leads to tumour growth inhibition due to the central involvement of the mTOR pathway in myriad cellular processes, including cell growth, cell survival, protein synthesis and angiogenesis." (PMID 32704173, 2020). "In general, the activation of EGF and VEGF receptors (EGFR and VEGFR) stimulates the Ras/Raf/MAPK kinase (MEK)/MAPK signaling cascade, which is involved in tumor progression or the PI3K/Akt/mammalian target of rapamycin (mTOR) cascade that promotes cell growth and the EMT." (PMID 32443915, 2020). "Similarly, overexpression of miR-223 showed significantly increased HepG2 and Bel-7402 apoptosis and acted as a tumor suppressor through mTOR signaling pathway." (PMID 32330203, 2020). "Impaired NOTCH1 activity may result in the activation of specific oncogenes (c-MYC, NFkB, or mTOR) or inhibition of tumor suppressor expression (FBXW7, PTEN, CDKN1B)." (PMID 32766158, 2020). "It is likely that targeting PI3K/mTOR signaling at different nodes in the pathway may have different affects on tumor progression depending on the driving alteration." (PMID 32795346, 2020). "In addition, the mammalian target of rapamycin (mTOR) positively regulates glycolysis in tumor-infiltrating M-MDSCs, accompanied by strong immunosuppressive activity, which can be counteracted by treatment with rapamycin (RPM)." (PMID 32325683, 2020). "Combination treatment with a second small molecule inhibitor such as mTOR inhibition could be a way of overcoming inter- and intra tumor heterogeneity but as yet the role of TKIs in first line treatment has not been evaluated." (PMID 32373525, 2020). "CCL5 promotes tumor cell proliferation through the mTOR pathway or increases glucose uptake." (PMID 33173412, 2020). "AMPK inhibits mTOR and improves metabolic reprograming, which consequently suppresses tumor growth." (PMID 31952173, 2020). "However, overactive PI3K/Akt/mTOR signaling makes tumor cells avoid cytotoxicity and resist treatment." (PMID 32041519, 2020). "IHC and IF analyses of tumor sections revealed a reduction in the TF activity marker fibrin and a decreased stromal collagen distribution, which are consistent with mTOR inhibitor-treated tumors." (PMID 32923403, 2020). "Pharmacological targeting of the mTOR-TF axis improves tumor microenvironment for therapy response." (PMID 32923403, 2020). "This review highlights the progress for targeting PI3K/AKT/mTOR-dependent mechanisms in GISTs and explores the relationship between mTOR downstream eIFs and the development of GISTs, which may be a promising future therapeutic target for this tumor entity." (PMID 33066449, 2020). "This review also introduces the role of mTOR signaling in tumors of various organs and the research progress on the application of mTOR inhibitors in tumors, which indicates the importance of the mTOR signaling pathway in the tumor fields." (PMID 32175074, 2020).
tumor (continued). "Antitumor drugs such as docetaxel, cisplatin often break the balance of oxidant and antioxidant systems, damage mitochondrial membrane potential, increase ROS production and silence some signaling pathways such as Akt/mTOR signaling pathway to lead to tumor cell apoptosis." (PMID 32576206, 2020). "Furthermore, the combination of MNK and mTOR inhibitors increases anti-tumor response by inhibiting cell proliferation and inducing apoptosis compared to monotherapy, which has increased the studies driven to the use of combined therapies." (PMID 32340135, 2020). "Tissue factor is a functional target of mTOR in tumor microenvironment." (PMID 32923403, 2020). "However, the conditions in tumours characterized by a strong activation of the Hh and/or mTOR signalling cascades are completely different than those in healthy tissue." (PMID 32751882, 2020). "Our data suggest that miR-3135b is a novel tumor suppressor with a potential role in the regulation of the GOLPH3/AKT1/mTOR axis to maintain Golgi integrity, which adds a piece in the puzzle of the novel cytoplasmic DNA damage response to DNA-damaging agents in CRC cells." (PMID 32601379, 2020). "Rapamycin (RPM) is an mTOR inhibitor (mTORi) and has been proved to have anti-tumor activity." (PMID 32751889, 2020). "Moreover, luteolin was shown to sensitize tumor cells to erlotinib through downregulation of EGFR/PI3K/AKT/mTOR signaling pathway and increased apoptosis." (PMID 31936346, 2020). "Therefore, mTOR inhibitors can enhance the efficacy of tumor immunotherapy by extending the life span of DC, improving antigen presentation and antigen processing ability." (PMID 32175074, 2020). "In this study, for the first time, we validated that the combination of ZA and rapamycin, targeting on the mTOR and mevalonate pathways, could eliminate the tumors and inhibit tumor recurrence in the LAM mouse models." (PMID 32063747, 2020). "Interestingly, recent evidence suggests that HCQ in combination treatment with mTOR inhibitors such as temsirolimus significantly suppresses tumour growth in vitro and in vivo." (PMID 32935427, 2020). "To wit, some in vitro studies suggest that PBM may favor tumor progression of oral SCC cells by activation of Akt/mTOR pathway, cellular proliferation, and cellular migration, while other studies report a reduction in tumor growth." (PMID 33107198, 2020). "Collectively, our results suggest that apigenin may inhibit tumor growth through the ER-mediated PI3K/Akt/mTOR pathway and that it can also attenuate the effects of histamine on tumors." (PMID 32340124, 2020). "The high pre-treatment infiltration of immune cells in responsive tumors might mirror their high intrinsic basal mTOR activation, reported to be involved in the recruitment of immune cell in the tumor microenvironment." (PMID 32770287, 2020). "The tumor cells may lose the sensitivity to the inhibitory effects induced by RAD001 on typical mTOR signaling pathways." (PMID 32373532, 2020). "Although autophagy sustains tumor metabolism and growth during Ras-induced transformation and tumorigenesis, compelling evidence suggests that onco-suppressors mediate autophagy process particularly targeting mTOR." (PMID 32708484, 2020). "The PI3K/AKT/mTOR pathway is a crucial and intensively explored intracellular signaling pathway in tumorigenesis, playing a key role in regulating cellular metabolism, tumor development, growth, proliferation, metastasis, and cytoskeletal reorganization." (PMID 32753611, 2020). "Moreover, AMPK has been demonstrated to be a major negative regulator of the mTOR pathway and to regulate tumor cell growth and apoptosis." (PMID 31894839, 2020). "PI3K/AKT/mTOR is one of the key pathways involved in the tumor chemoresistance development." (PMID 33142817, 2020). "We evaluated the expression of p-Akt, and p-mTOR in tumor tissues after DMC-BH treatment." (PMID 33221748, 2020).
tumor (continued). "Since hypoxia and Hypoxia Inducible Factor-1 (HIF-1) have been associated with treatment failure and tumor progression, we hypothesized that EGFR/mammalian Target of Rapamycin (mTOR)/HIF-1 axis inhibition could radiosensitize HNSCC." (PMID 31640284, 2019). "Interestingly, this patient was not responsive to immune checkpoint inhibition, in spite of high PD-L1 and tumor mutational burden (TMB), but surprisingly it showed an exceptional response to an mTOR inhibitor." (PMID 31500143, 2019). "Of them, several reports have provided the molecular analysis and showed the anti-tumor proliferation mechanism by western blot assay, through downregulating the phosphorylation of mTOR pathway proteins such as p70S6K, and S6, and upregulating the phosphorylation of 4EBP131–33." (PMID 31601917, 2019). "Akt/mTOR signaling regulates tumor progression and autophagy." (PMID 31724536, 2019). "To verify whether circNRIP1 plays a tumour promotor role via the AKT/mTOR pathway by sponging miR-149-5p, we attempted to detect the expression level of AKT1, the target of miR-149-5p, in GC cells." (PMID 30717751, 2019). "In TNBC tumor cells, mTOR signaling is frequently upregulated." (PMID 31388935, 2019). "This central function of mTOR in metabolic reprogramming could be targeted using mTOR inhibitors and thus prevent tumor growth and malignancy." (PMID 31817676, 2019). "CC-115, a dual inhibitor of DNA-PK and mammalian target of rapamycin (mTOR), is being tested; preliminary anti-tumor activity has been reported, although whether these responses are attributable to activity against DNA-PK or mTOR is unclear." (PMID 31649878, 2019). "Finally, BSN not only suppressed constitutive, but also inducible phosphoinositide-3-kinase (PI3K)/protein kinase B (Akt)/mammalian target of rapamycin (mTOR) phosphorylation in tumor cells." (PMID 31013639, 2019). "The inhibition of mTOR activation can induce autophagy in tumor tissues." (PMID 31929797, 2019). "Future studies may explore the effect of mTOR tissue expression after tumour ablation and its relationship with tumour recurrence." (PMID 30650598, 2019). "Mutations in NF1, TSC2 or PTEN-encoding for key suppressor genes of this pathway, and altered expression of the mTOR pathway components, are common hallmarks of a great proportion of NETs, wherein these alterations seem to be directly related with tumour development and progression." (PMID 31443481, 2019). "AMPK/mTOR pathway plays an important role in the NPs induced inhibition of tumor growth." (PMID 31001120, 2019). "mTORC1 (mTOR complex consisting of mTORC1 and mTORC2) is reported to accelerate tumour growth by promoting a shift to the Warburg effect, which likely facilitates the incorporation of nutrients into new bio-products to sustain the highly proliferative character of GC cells." (PMID 30717751, 2019). "Therefore, the anti-tumor activity of PCC0208027 was associated with the simultaneous inhibition of EGFR and HER2 activation and blockade of RAF/MEK/ERK and AKT/mTOR signaling pathways." (PMID 30952931, 2019). "Moreover, HPV E6/E7 mouse models develop SCC lesions with high mTOR activation, and, unsurprisingly, tumour development was abolished using the mTOR inhibitor Rapamycin." (PMID 30970654, 2019). "We speculated that the activated PI3K/AKT/mTOR signaling pathways might serve as a responsive feedback to LDM‐induced DSBs in tumor cells." (PMID 30681288, 2019). "Furthermore, it has been reported that co-targeting mTOR and PD-L1 enhances tumour growth inhibition in a syngeneic oral cancer mouse model." (PMID 30970654, 2019). "Combination of CDK4/6 and mTOR inhibitors synergistically inhibits tumor growth." (PMID 31277692, 2019). "Loss of neurofibromin is considered a tumor-promoting event that leads to RAS hyperactivity and the consequent activation of multiple downstream survival and proliferative pathways, including MAPK, mTOR, and Akt." (PMID 31416195, 2019).